PRDX6 (peroxiredoxin 6)
Diseases named in the same sentence as PRDX6 in open-access papers (continued):
Sharing a sentence is not in itself a finding about the gene and the disease.
glioma (3 papers, 2022 to 2024). A benign or malignant brain and spinal cord tumor that arises from glial cells (astrocytes, oligodendrocytes, ependymal cells). "Elevated Prdx6 expression is notably associated with a lower survival rate among patients, underscoring its pro-cancer effects in gliomas." (PMID 38671897, 2024). "In particular, overexpression of PRDX1, PRDX4, and PRDX6 has been reported in most histological glioma types compared to the normal tissues and correlated with poor survival of glioma patients." (PMID 38607010, 2024). "Research from glioma patients revealed a positive correlation between the Prdx6 level and increasing grades of gliomas." (PMID 38671897, 2024). "Prdx6 remains in a dormant state in a typical brain, while in some pathological states, such as glioma and AD, Prdx6 is selectively upregulated in astrocytes." (PMID 38671897, 2024). "Hence, Prdx6 may play pro-tumor roles in glioma development and could serve as a potential therapeutic target for gliomas." (PMID 38671897, 2024).
injury (3 papers, 2017 to 2024). Damage inflicted on the body as the direct or indirect result of an external force, with or without disruption of structural continuity. "However, PRDX6 may play protective role in LPS-induced tissue injury because PRDX6 deficiency exacerbates LPS-induced acute lung injury in mice through increasing oxidative stress." (PMID 28881633, 2017). "Studies have shown a dramatic increase in Prdx6 during mild to moderate TBI in a rat TBI model, which indicated that Prdx6 may be a candidate marker of acute mild brain injury." (PMID 38671897, 2024).
lupus (3 papers, 2023 to 2026). "Moreover, Prdx6-deficient mice demonstrated exacerbated imiquimod-induced lupus." (PMID 37189338, 2023). "This study aimed to demonstrate the potential of activated leukocyte cell adhesion molecule (ALCAM), hemopexin (HPX), and peroxiredoxin 6 (PRDX6) as urine biomarkers for systemic lupus erythematosus (SLE)." (PMID 38915417, 2024). "Patients with SLE and patients with lupus nephritis (LN) showed significantly elevated ALCAM, HPX, and PRDX6 levels compared with HCs." (PMID 38915417, 2024).
non-small cell lung carcinoma (3 papers, 2022 to 2024). A group of at least three distinct histological types of lung cancer, including non-small cell squamous cell carcinoma, adenocarcinoma, and large cell carcinoma. "High levels of PRDX6 expression were detected in samples of tumor tissue from non-small cell lung cancer patients, and expression of PRDX6 presented a positive relationship." (PMID 38544826, 2024). "Furthermore, to verify if the interaction between FTH1 and PRDX6 is independent by cell lines, we replicated the same experiment in non-small cell lung cancer (NSCLC) NCI-H460 cells, transiently transfected with 3xFlag-FTH1 or 3xFlag control vector." (PMID 36361777, 2022).
Oral squamous cell carcinoma (3 papers, 2023 to 2025). "In addition, PRDX1, PRDX2, and PRDX6 have also been reported to be overexpressed in oral squamous cell carcinoma." (PMID 36969053, 2023). "Oral squamous cell carcinoma was indicated to have overexpression of PRDX1, PRDX2, and PRDX6." (PMID 40281661, 2025).
pancreatic cancer (3 papers, 2013 to 2024). "We found that loss of PRDX6 from two pancreatic cancer cell lines suppressed growth, a phenomenon reversed by the addition of selenium or liproxstatin-1." (PMID 38867112, 2024). "Database analysis also revealed that expression of PRDX6 is high in pancreatic cancer and that high expression correlates with a poor prognosis." (PMID 38867112, 2024).
periodontitis (3 papers, 2022 to 2025). An acute or chronic inflammatory process that affects the tissues that surround and support the teeth. "Peroxiredoxin 6 alleviated LPS-induced inflammation and ferroptosis in periodontitis via regulating NRF2 signaling." (PMID 40066457, 2025). "The use of an antioxidant enzyme, Peroxiredoxin 6, has been reported to reduce lipopolysaccharide-induced inflammation and ferroptosis in periodontitis." (PMID 36359745, 2022). "Peroxiredoxin 6 (PRDX6), which is regulated by Nrf2, helps reduce LPS-induced inflammation and ferroptosis, thereby slowing periodontitis progression." (PMID 40541947, 2025).
prion disease (3 papers, 2012 to 2024). A transmissible disease that is caused by a protein that is able to induce abnormal folding of normal cellular proteins, leading to characteristic spongiform brain changes, which are associated with neuronal loss without an inflammatory response. "The loss of the Prdx6 protein exacerbated the prion disease, which mainly manifested as astrogliosis and an accumulation of proteinase K-resistant PrPSc, while the overexpression of Prdx6 improved cognitive behavior and attenuated prion-related astrocytosis." (PMID 38671897, 2024). "Overall, although most studies elucidate the elevated levels of Prdx6 in prion diseases, its role remains somewhat controversial, so additional studies are needed to provide insights into the potential value of Prdx6 in prion diseases." (PMID 38671897, 2024). "Sporadic Creutzfeldt–Jakob disease (sCJD) is one of many prion diseases characterized by the spontaneous formation of misfolded prion proteins in the brain, and the expression of Prdx6 was increased in the frontal cortex of patients with sCJD." (PMID 38671897, 2024). "Together with our study, those data point to PRDX6 activities as new important players in the pathogenesis of prion diseases." (PMID 23210548, 2012). "Studies have shown that Prdx6 is consumed by peroxides produced by prion-induced oxidative stress, which prevents the emergence of prion-related neuropathology in Prdx6 transgenic mice with prion disease." (PMID 38671897, 2024).
anaplastic thyroid cancer (2 papers, 2015 to 2022). "PRDX1, PRDX2, and PRDX3 expressions downregulated in papillary and anaplastic thyroid cancers, PRDX4 mRNA expression was moderately increased in anaplastic thyroid cancer tissues, and PRDX6 expression status showed similar levels as well as normal thyroid and thyroid cancers." (PMID 35571253, 2022). "PRDX1, PRDX2, and PRDX3 mRNA synthesis decreased in papillary and anaplastic thyroid cancers, PRDX4 mRNA expression was moderately increased in anaplastic thyroid cancer tissues, and PRDX6 expression status was at similar levels in normal thyroid and thyroid cancers." (PMID 26664298, 2015).
cerebral infarction (2 papers, 2017 to 2024). An ischemic condition of the brain, producing a persistent focal neurological deficit in the area of distribution of the cerebral arteries. "Inhibiting the aiPLA2 activity of Prdx6 decreased the neurologic deficits, cerebral infarction, and inflammatory molecules." (PMID 38671897, 2024). "In vivo, combined treatment with Prdx6-iPLA2 activity inhibitor MJ33 showed a greater diminution in neurologic deficits, cerebral infarction, brain water content and inflammatory molecules than Prdx6-siRNA treatment alone." (PMID 28424593, 2017). "However, combined treatment with Prdx6 siRNA and Prdx6-iPLA2 inhibitor MJ33 showed a greater diminution in neurologic deficits, cerebral infarction, brain water content and inflammatory molecules than Prdx6-siRNA treatment alone." (PMID 28424593, 2017).
cortical dysplasia (2 papers, 2017 to 2024). "PRDX6 was identified as differentially expressed in epileptic brain tissues from patients with childhood cortical dysplasia." (PMID 38585359, 2024). "And FSCN1, CRMP1, NDRG1, DPYSL5, MAP4, and FABP3 were selected for validation and identified to be increased in childhood cortical dysplasia patients, while PRDX6 and PSAP were identified decreased." (PMID 28222113, 2017).
Epidermoid carcinoma (2 papers, 2022 to 2025). "The immunofluorescence (IF) results indicated that PRDX6 detected in the Plasma membrane and Cytosol in the human cancer cell lines of A-431 (Epidermoid carcinoma), U-2OS (Osteosarcoma), and U-251 MG (Glioblastoma)." (PMID 36120430, 2022).
Hepatic fibrosis (2 papers, 2023 to 2025). The presence of excessive fibrous connective tissue in the liver. "Specifically, both the protein and mRNA levels of PRDX6 are elicited in hepatic fibrosis induced by CCl4 after four weeks; however, eight weeks after the treatment, only the mRNA level of PRDX6 is increased while its protein level shows a comparative decrease." (PMID 40298631, 2025). "Notably, carbon tetrachloride (CCl4) has been reported to inhibit hepatic fibrosis but appears to modulate the PRDX6 expression bidirectionally." (PMID 40298631, 2025). "Therefore, NPM decreased ROS in HSCs by activating Akt or by upregulating PRDX6, thus protecting the activated HSCs from apoptosis and promoting liver fibrosis." (PMID 37648688, 2023).
influenza (2 papers, 2012 to 2022). An acute viral infection of the respiratory tract, occurring in isolated cases, in epidemics, or in pandemics; it is caused by serologically different strains of viruses (influenzaviruses) designated A, B, and C, has a 3-day incubation period, and usually lasts for 3 to 10 days. "Interestingly, despite the demand for antioxidants during inflammation, influenza caused depletion in two key antioxidants: Cat and Prdx6." (PMID 22355371, 2012). "Surprisingly, our staining demonstrated that Prdx6 expression in the lungs is indeed drastically changed following the influenza infection." (PMID 22355371, 2012). "Further studies on the mechanism of Prdx6 induction in AT1 cells and its potential role in suppressing influenza-induced apoptotic cell death are in progress." (PMID 22355371, 2012). "At 1 dpi, there was no change in Prdx6 and CCSP expression in NS1-positive Clara cells, which suggests that influenza replication does not directly impact the expression of these proteins." (PMID 22355371, 2012).
intrahepatic cholangiocarcinoma (2 papers, 2022 to 2025). A carcinoma that arises from the intrahepatic bile duct epithelium in any site of the intrahepatic biliary tree. "Additionally, PRDX6 knockout has been shown to suppress the malignant progression of intrahepatic cholangiocarcinoma." (PMID 40281661, 2025).
lung diseases (2 papers, 2016 to 2023). "Research has found that PRDX6 is important in tumor development, cardiovascular diseases, neurological disorders, inflammatory conditions, and lung diseases." (PMID 37554330, 2023). "Up-regulation of PLA2 activity was related with fibrosing lung diseases, and inhibition of PLA2 activity of Prdx6 reduced NOX2-activated ROS generation in lung ischemia/reperfusion model." (PMID 26872211, 2016).
lung fibrosis (2 papers, 2016 to 2023). "All of these, except for Prdx6, were highly abundant in BALF of control mice under basal conditions (left-hand panel) and Gpx3 and Sod3 were additionally upregulated in BALF during bleomycin-induced lung fibrosis." (PMID 27435875, 2016).
non-alcoholic steatohepatitis (2 papers, 2019 to 2024). "In non-alcoholic steatohepatitis (NASH), the interaction between Miz1 and Prdx6 in hepatocytes is crucial." (PMID 38671897, 2024).
papillary thyroid carcinomas (2 papers, 2014 to 2016). "The 1-Cys Prdx6 has been characterized as a tumor inhibitor because it protects mice and human skin cells against lipid peroxidation, and the levels of this protein are lower in papillary thyroid carcinomas than in normal thyroid tissue." (PMID 25329795, 2014). "PRDX6 presented reduced levels in papillary thyroid carcinomas compared to non-neoplastic tissues." (PMID 27206673, 2016).
pulmonary hypertension (2 papers, 2023 to 2025). Increased pressure within the pulmonary circulation due to lung or heart disorder. "In other studies using MCT to establish a rat model of pulmonary hypertension (PH), peroxiredoxin 6 (PRDX6) was found to regulate ferroptosis in PAECs through HMGB1 release and activation of the TLR4/NLRP3 inflammasome signaling pathway." (PMID 38111578, 2023).
scrapie (2 papers, 2012 to 2021). A fatal disease of the nervous system in sheep and goats, characterized by pruritus, debility, and locomotor incoordination. "A study by Wagner and co-workers showed that PRDX6 was upregulated in scrapie-infected mice and neuronal cell lines." (PMID 34394070, 2021). "Although we cannot exclude the possibility that PRDX1, 3 or 4 of the 2-Cys PRDX subgroup were slightly regulated, it is obvious that PRDX6 was strongly affected in scrapie-infected mice brains." (PMID 23210548, 2012). "Apolipoprotein E and peroxiredoxin 6 (PRDX6) were identified as upregulated proteins in brains of scrapie-infected mice and cultured neuronal cell lines." (PMID 23210548, 2012). "Correspondingly to scrapie-infected mice, an upregulation of PRDX6 was observed in scrapie-infected N2a58/22L cells as shown by Western blot analysis." (PMID 23210548, 2012). "Next, we aimed at the investigation of PRDX6 expression in scrapie-infected neuronal cells." (PMID 23210548, 2012). "Quantification of PRDX6 protein expression in brains of four individual mice at each time point after infection indicated that the observed effect was statistically significant and reproducibly observed in scrapie-infected mice." (PMID 23210548, 2012). "Interestingly, PRDX6, a protein that directly networks with our downregulated PRDX1, was shown to be upregulated in scrapie-infected mice and neuronal cell lines and controls expression of PrPC and PrPSc in neuronal cells." (PMID 34394070, 2021).
skin tumor (2 papers, 2014 to 2015). "Overexpression of PRDX6 leads to significantly reduced levels of oxidized lipids in mice and results in a reduced rate of UVB and UVA induced apoptosis, whereas loss of PRDX6 leads to an increased skin tumor rate." (PMID 25906193, 2015). "Therefore, it will be important to determine if individuals with strong PRDX6 expression in normal skin are less susceptible to tumor development and vice versa, and if PRDX6 overexpression in skin tumors correlates with tumor aggressiveness." (PMID 25594034, 2014). "Based on these data, we analyzed the function of Prdx6 in skin tumorigenesis using genetic and chemically-induced skin cancer models." (PMID 25594034, 2014).
steatosis (2 papers, 2019 to 2022). Increased lipid within the cytoplasm of cells. "The C57BL/6J‐Tg transgenic mice with increased PRDX6 expression prevented the liver from developing steatosis, suggesting that PRDX6 may contribute directly to the regulation of hepatic lipid accumulation." (PMID 34327606, 2022). "Based on these results, we may suggest that the steatosis state in the absence of PRDX6 and on HFD could be a consequence of hepatic lipid overload." (PMID 31949886, 2019). "The inverse relationship between PRDX6 abundance and hepatic TAG and the increasing levels of PRDX6 in response to the glucose challenge when hepatic TAG levels are decreasing suggests that PRDX6 may protect the liver from steatosis derived from TAG accumulation." (PMID 34327606, 2022).
type 1 diabetes (2 papers, 2020 to 2021). "In this article, we describe a beneficial effect of peroxiredoxin 6 (PRDX6) in a type 1 diabetes mouse model." (PMID 32908936, 2020).
amyloidosis (1 paper, 2024). A disorder characterized by the localized or diffuse accumulation of amyloid protein in various anatomic sites. "The overexpression of Prdx6 in AD mice promotes amyloidosis and increases oxidative stress, thereby expediting the progression of AD." (PMID 38671897, 2024). "Thiacremonone influences Prdx6 expression levels and oxidative stress, thereby protecting against amyloidosis and memory dysfunction and inhibiting the development and progression of AD." (PMID 38671897, 2024).
aneurysm (1 paper, 2019). Bulging or ballooning in an area of an artery secondary to arterial wall weakening. "Conversely, environments with a high inflammation and oxidative stress load, such as aortic lesions or aneurysms, can cause post-translation modification of Prdx6, such that it loses its antioxidant activity." (PMID 30871234, 2019). "In patients with abdominal aortic aneurysms, there are increased levels of Prdx6, both in the plasma and in the tissue from the aneurysm." (PMID 30871234, 2019).
autoimmune disease (1 paper, 2024). A disorder resulting from loss of function or tissue destruction of an organ or multiple organs, arising from humoral or cellular immune responses of the individual to their own tissue constituents. "In this study, an increase in PRDX6 was observed in SLE and LN, suggesting a predominant inflammatory response through the elevated oxidative stress-mediated signaling pathway, which is consistent with findings in some autoimmune diseases." (PMID 38915417, 2024).
bipolar disorder (1 paper, 2024). A disorder of the brain that causes unusual shifts in mood, energy, activity levels and the ability to carry out day-to-day tasks. "Little is known about the role of Prdx6 in ASD and bipolar disorder." (PMID 39727940, 2024).
bladder tumor (1 paper, 2023). "Additionally, there is direct evidence that PRDX6 modulates the JAK-STAT3 pathway which enhances the proliferation of bladder tumor cells." (PMID 37501157, 2023).
bladder urothelial carcinoma (1 paper, 2021). "Therefore, the present study sought to explore the molecular characteristics and potential clinical significance of PRDX family members in pan cancer and further validate the function of PRDX6 in bladder urothelial carcinoma (BLCA)." (PMID 34246267, 2021).
brucellosis (1 paper, 2019). Brucellosis is a bacterial infection that spreads from animals to people via unpasteurized dairy products or by exposure to contaminated animal products or infected animals. "In this study, according to our previous work, we focused on the relationship between Prdx6 and brucellosis." (PMID 31438945, 2019). "Elucidation of the relationship between host Prdx6 and Brucella and the mechanism involved may facilitate the prevention and treatment of brucellosis in the future." (PMID 31438945, 2019).
cerebral amyloid angiopathy (1 paper, 2020). "Similarly, expression of PRDX6 by activated, perivascular astrocytes has been described in AD autopsy material, including vessels which do not exhibit overt cerebral amyloid angiopathy." (PMID 32907613, 2020).
Chronic colitis (1 paper, 2025). A chronic inflammatory disease of the large intestine (colon, cecum and rectum). "Additionally, other Prdxs may also be involved in intestinal inflammation, as evidenced by the protective effects observed in Prdx6-deficient mice in models of acute and chronic colitis." (PMID 40715057, 2025).
cognitive decline (1 paper, 2024). "Elevations in GFAP, NF-L, and PRDX-6 point to a cycle of BBB disruption, axonal injury, oxidative stress, and neuroinflammation—factors that are closely linked to cognitive decline and neurodegenerative diseases." (PMID 39766495, 2024).
dengue (1 paper, 2022). "aegypti dengue-susceptible (Cali-S) strain to a dengue-resistant (Cali-MIB) strain at 30 hpi, however, the peroxiredoxin-6 (prx-6) was exclusively expressed in the Cali-MIB strain, but was down-regulated upon DENV infection." (PMID 35006065, 2022).
dental caries (1 paper, 2018). The decay of a tooth, in which it becomes softened, discolored, and/or porous. "As a result of MRM, 14 age-specific proteins were verified to be associated with dental caries, among which glutathione S-transferase P, peroxiredoxin-6, WD repeat-containing protein 1, and glucose-6-phosphate isomerase exhibited complex interactions with each other." (PMID 30359274, 2018).
diffuse large B-cell lymphoma (1 paper, 2018). "Another study suggested that high level of PRDX6 was correlated with shorter 5-year disease-specific survival in patients with diffuse large B-cell lymphoma." (PMID 30104402, 2018).